NF2 (NF2, moesin-ezrin-radixin like (MERLIN) tumor suppressor)
Diseases named in the same sentence as NF2 in open-access papers (continued):
Sharing a sentence is not in itself a finding about the gene and the disease.
tumor (continued). "Given that NF2 mutation was not seen and that chromosome 22 deletion is not a shared feature in these tumors, we believe that one or more other tumor suppressor genes or oncogenes is responsible for the tumor initiation of familial multiple meningioma." (PMID 19589153, 2009). "Although the prevalence and consistency of these alterations remain under investigation, epigenetic regulation may offer additional insight into the heterogeneity of NF2-related tumour behaviour and represent a potential target for future therapeutic strategies." (PMID 40843672, 2025). "Whether or not such a complex mass of axons constitutes a discrete tumor, meaning that the NF2 gene has been mutated, is beyond the scope of this paper." (PMID 41300330, 2025). "While a subtotal resection may increase the chances of preserving the CN function, it may also lead to recurrence or growth of the residual tumor which may impair the CI outcome in the long term, especially in NF2 cases which are more prone to recurrence and tumor growth." (PMID 39914046, 2025). "Germline testing for NF2 was negative, confirming somatic NF2 mutation only in the tumor." (PMID 39917261, 2025). "However, a number of studies suggested that non-NF2-SWN patients might experience milder functional impairments and fewer tumour-related symptoms compared to NF2-SWN patients." (PMID 40510571, 2025). "Moreover, these NF2-EVs are capable of enhancing tumor cell proliferation." (PMID 41149489, 2025). "Similarly, complete NF2 deletion rescues Hippo ‘off’ state activity, leading to tumor progression." (PMID 39796693, 2024). "However, in patients with NF2, these treatment options are very limited due to the higher invasiveness of the tumors and cumulative morbidity after multiple interventions and because of tumor burden." (PMID 38817895, 2024). "However, we cannot entirely rule out that among the cases with NF2 mutations detected in tumor material, there were more cases with NF2, as complete clinical records were not available for all patients and germline testing was not performed." (PMID 38265489, 2024). "Furthermore, expression of NF2, another tumor suppressor, was increased after DDR2 RNAi." (PMID 38538106, 2024). "All tumours with NAB2-STAT6 gene fusion had limited CNAs unlike tumours with NF2 mutations." (PMID 36882706, 2023). "A possible explanation for the difference in local tumor control and treatment-related toxicity after PRT, between sporadic VS and the NF2-related VS, is that NF2-linked tumors may be less sensitive to radiation therapy, especially in the context of a more aggressive NF2 phenotype." (PMID 36975476, 2023). "However, the clinical course of tumor growth and hearing deterioration were not predicted only by germline pathogenic NF2 variants." (PMID 37087513, 2023). "CNVs deleting NF2 on chromosome 22q are early events underlying Immune-enriched or Hypermitotic meningioma tumorigenesis, but Merlin-intact meningiomas encode SSVs targeting TRAF7, AKT1, or KLF4 that may be tumor-initiating." (PMID 36993679, 2023).
tumor (continued). "Collaborating these reports and our result, we speculate that the difference in the prognostic implication of NF2 alteration between supra- and infratentorial space may be attributed to the spatial distribution of the tumour cell of origin (neural crest vs mesoderm)." (PMID 35570314, 2022). "Univariate Cox proportional hazards analysis revealed that NF2 alteration/22q loss (hazard ratio [HR], 16.8; 95% confidence interval [CI], 2.1–137.0; p = 0.009) and MIB-1 LI > 4 (HR, 4.2; 95% CI, 1.05–16.9; p = 0.04) were significantly associated with tumor recurrence." (PMID 35804955, 2022). "7/18 NF2 and 1/23 SWNT patients were identified to be mosaic cases with positive tumor DNA analysis and in 1/18 NF2 and 15/23 SWNT patients no mutation could be detected neither in blood nor in tumor DNA." (PMID 35771312, 2022). "NF1 and NF2 encode tumour suppressors that have been experimentally implicated in RAF inhibitor resistance in epithelial cancer cells and downregulation of either or both Nf1 or Nf2 in Ba/F3 cells stably expressing BRAFV600E conferred vemurafenib resistance in vitro." (PMID 35158965, 2022). "Even if the clinical consequences of the mutations of NF2 gene strongly suggest that it is a tumor suppressor gene, the biological role of the merlin is not documented enough to consider it as directly involved in DNA damage repair and signaling and/or in the cell cycle checkpoint control." (PMID 36551628, 2022). "NF2/YAP signaling may be a potential target for the treatment of tumor cells." (PMID 34123855, 2021). "Furthermore, the molecular features of the tumours were found to resemble that of human MM tumours, including activation of Akt; homozygous deletion of tumour suppressor genes p16 (Ink4A), p14 (ARF)/p19(Arf), and p15(Ink4B); and loss of the Nf2 protein, Merlin." (PMID 34900693, 2021). "Furthermore, NF2 deletions are also found in other tumor types such as renal cell carcinoma, cervical squamous cell carcinoma, schwannomas and meningiomas, which may hence respond equally well to the inhibition of YAP1 activation." (PMID 34685695, 2021). "However, there was no obvious association between change in tumor size and NF2 alterations observed in this study." (PMID 33660194, 2021). "We therefore used microdissected tumor samples of eight recurrent irradiated VS (five sporadic and three NF2-associated VS) and compared them with 49 non-irradiated controls (36 sporadic and 13 NF2-associated VS)." (PMID 31936793, 2020). "This NF2 mutation was not present in a tumor biopsy (cfDNA was not available)." (PMID 32642718, 2020). "Interestingly, we did not observe any somatic point mutations in the tumor (NF2 was somatically inactivated via chromosome 22 deletion)." (PMID 32724039, 2020). "Only in three patients, no NF2 mutations were found neither in tumor nor in blood DNA." (PMID 32537663, 2020). "Activation of NF2 expression may promote tumor cell apoptosis, inhibit tumor growth and metastasis." (PMID 32337368, 2020). "However, both STX agents and Pak inhibitors can promote apoptosis in NF2 tumour cells." (PMID 31730023, 2019). "In addition, the frequency of NF2 aberrations increases with tumor grade." (PMID 31970090, 2019). "Mutations in the Nf2 gene also contribute significantly to sporadic schwannomas; 66% of sporadic vestibular schwannomas were found to have mutations in this gene (such mutations are non-germline mutations, occurring in the tumor but not in the germline)." (PMID 31632194, 2019). "Interestingly, early clinical outcomes data in these patients suggest that non-tumor ABI users may benefit more than NF2 patients." (PMID 30760974, 2019).
tumor (continued). "Thus, we did not observe an association between the tumor status and NF2 alterations reported in other cohorts." (PMID 31565188, 2019). "Therefore, we intend to assess the prognostic impact of the NF2 gene alterations on tumour growth." (PMID 28710469, 2017). "Many cancer-related genes were rearranged, such as the region containing the tumour suppressor NF2 and a copy gain for ERBB3, a member of the epidermal growth factor receptor family of receptor tyrosine kinases implicated in proliferation and invasion of tumours in humans." (PMID 28821767, 2017). "A total of 34 samples with unknown NF2 genotype (30 blood DNAs and 4 tumor DNAs) were analyzed." (PMID 26066488, 2015). "We hypothesise that in VS these multiple sites of origin of VS go some way to explaining the difference in phenotypical description of a multilobulated tumour that appears like a ‘bunch of grapes’.7, 8 In NF2, as the tumours grow they eventually coalesce into one tumour mass." (PMID 26104281, 2015). "However, here we examine the role of the NF2 protein as a tumor suppressor, rather than its loss of function." (PMID 23308224, 2013). "However, consistent with the fact that not all tumors carry a mutated Nf2 gene, distinct signaling pathways that inactivate the Hippo pathway and favor tumor development have been described." (PMID 24260485, 2013). "Recent translational work has highlighted the relevance of the tumor microenvironment and recurrent genomic alterations such as BAP1, NF2, and CDKN2A in shaping immune activity and potentially modulating response to immune checkpoint inhibitors." (PMID 41744857, 2026). "In conclusion, this study confirms the elevated expression of microRNA‐223‐3p in PTC tissues, its correlation with tumor staging, and its role in promoting PTC cell proliferation, migration, invasion, and EMT through targeting NF2." (PMID 39712860, 2025). "New important data demonstrated that NF2 inactivation drove the activation of p21-activated kinases (PAKs) signaling, which initiated NF1-mutant SC tumor dedifferentiation and resistance to therapy." (PMID 40940747, 2025). "Multiple studies have trialled the use of bevacizumab, an inhibitor of angiogenesis, in NF2 SWN-related VS and found a reduction in tumour growth and hearing stabilisation or improvement." (PMID 40140675, 2025). "Also, NF2-associated optic-orbital pathologies, such as tumor lesions in the orbit, non-tumorous eye malposition, etc., may confound ONSD." (PMID 40820211, 2025). "Collectively, our results provide insight into the immunological configuration of NF2 SWN VS tumours and suggest tumour region-specific pathways that are potential therapeutic targets for the disease." (PMID 40140675, 2025). "Epigenetic alterations, particularly DNA methylation, histone modifications, and the dysregulation of ncRNAs, have been shown to influence key cellular pathways relevant to tumour development, progression, and clinical heterogeneity in NF1 and NF2." (PMID 40843672, 2025). "NF2-SWN and sporadic forms of both tumour types showed similar predicted abundance of immune cells from the bulk deconvolution." (PMID 41437121, 2025). "Taken together, these results show that the NF2 LOF mutants induce cell transformation and tumor growth by activating the VANGL-JNK pathway." (PMID 39572544, 2024). "At baseline before the trial, patients with NF2 tended to have lower baseline QOL than literature normal values, which can be attributed to the effect of tumor burden interfering with daily functional activities." (PMID 38372904, 2024).
tumor (continued). "NF2 functions in a complex with WWC1 (Kibra) and FRMD6 as an upstream effector of the Hippo pathway in order to regulate cell growth and suppress tumor development." (PMID 38920690, 2024). "On the other hand, TEAD can play an important role in tumor progression, metastasis, tumor metabolism, immunity and drug resistance through transcription and regulation of KRAS, BRAF, LKB1, NF2 and MYC." (PMID 38553612, 2024). "Further analysis of individual spots revealed a significant positive correlation between tumor infiltration by NK cells (CD56+) and average BAP1, NF2, MTAP, and LAG3 expression levels in MPM (ρ > 0.4)." (PMID 38994676, 2024). "The fingerprint fp160 composed of three clinical parameters: Gleason primary score, tumor stage, psa, and two molecular protein expression levels for CDKN1B and NF2 has emerged as very concise and performant." (PMID 37188913, 2023). "Vestibular function in patients with VS/NF2-SWN was comparedwith that in normal subjects and patients with sporadic, unilateral VS tumours." (PMID 37025569, 2023). "To conclude, the data generated in this study identify strong similarities in NF2-SWN and sporadic VS from their bulk transcriptomic profiles, enriched immune-related signalling pathways and overall abundances of tumour immune microenvironment components." (PMID 37680691, 2023). "The study presented here aimed to interrogate and compare the immune compartments between NF2-SWN and sporadic VS to characterize similarities or differences in their tumour immune microenvironments." (PMID 37680691, 2023). "Alterations of NF2 (40%) and FBXW7 (30%) were also identified in tumors only, indicating a heterogeneity of tumor cells and clonal selection process in some patient-derived cell lines during the expansion process in vitro." (PMID 37345150, 2023). "Vestibular symmetry was biased towards the tumour in sVS, was nullin patients with VS/NF2-SWN and within VS/NF2-SWN was biased towards the tumour in theunilateral patients but towards the smaller tumour (ST) in bilateral patients." (PMID 37025569, 2023). "NF2 (moesin–ezrin–radixin-like [MERLIN] tumor suppressor) is frequently inactivated in cancer, where its NF2 tumor suppressor functionality is tightly coupled to protein conformation." (PMID 37280085, 2023). "While a patient-derived point mutant of NF2 FERM domain (NF2m) was found to strongly inhibit nucleic acid recognition and subsequent anti-tumor immunity." (PMID 36860877, 2023). "Given that NF2-SWN is a rare disease and sporadic tumours that need additional treatment options are also rare, it would be advantageous to find appropriate treatment targets applicable to both groups for preclinical and clinical trial drug development." (PMID 37680691, 2023). "Here, we validated the two tumor suppressor genes, STK11 and NF2, involved in the mTOR signaling pathway which have been suggested as promising oncogenic therapeutic targets in recent studies." (PMID 37351538, 2023). "Only three genes were mutated in more than two tumor samples-CDC27 (part of the anaphase-promoting complex, tumor suppressor), USP8 (deubiquitinase gene, cell cycle involvement), and NF2." (PMID 36672540, 2022). "Significant focal copy number changes as identified by GISTIC analysis (q-value of < 0.001) occurred on chromosomes 3, 9, 16 and 22 in regions that contain tumour suppressor genes, BAP1 (chr3), CDKN2A (chr9) and NF2 (chr22)." (PMID 35637530, 2022). "NF2, also known as MERLIN, is a tumour suppressor and functions as an upstream positive regulator of the Hippo pathway kinases." (PMID 35702882, 2022). "Taken with other Hippo pathway members (NF2, LATS1 and LATS2), 50% of tumours had at least one lesion of this pathway." (PMID 34580349, 2021).
tumor (continued). "We also found clonal indels in NF2 in two tumors (cdRCC and mixRCC), and MET (mixRCC), SMARCB1 (pRCC1) and ROS1 (pRCC2) indels in one tumor each." (PMID 32555180, 2020). "Genes positively selected under both conditions were enriched for known tumor suppressors, such as NF1 and NF2, as expected." (PMID 32413516, 2020). "Additionally, the NF2 gene may have implications for the tumor microenvironment." (PMID 32982948, 2020). "In a NF2-mutant sRCC model, YAP1 knockdown and NF2 reconstitution suppressed cell proliferation, tumour growth and invasion, both in vitro and in vivo." (PMID 31959902, 2020). "Overexpression of the NF2 gene in NIH3T3 cells decreases their growth rate, confirming the role of NF2 as a tumor suppressor." (PMID 33065998, 2020). "MYPT1-PP1 was shown to dephosphorylate Merlin/NF2 at serine 518, thereby leading to the activation of the kinase cascade that leads to YAP/TAZ inhibition and preventing tumor progression." (PMID 31926547, 2020). "Neurofibromatosis 2 (Nf2, OMIM 101000) is a tumor suppressor that inhibits YAP during dorsal root ganglia (DRG) development." (PMID 32850790, 2020). "Neurofibromin 2 (NF2), a potent tumor suppressor, is reported to inhibit proliferation in several cell types." (PMID 32422606, 2020). "Tumour growth in NF2 cells is affected by different inhibitors from those affecting NF1 growth pathways: specifically, NF2 cells are affected by merlin-downstream pathway inhibitors." (PMID 31730023, 2019). "Beyond NF2, expanded indications for ABI implantation have been explored in non-tumor adults and children and there are, a handful of clinical studies in the United States and abroad." (PMID 30760974, 2019). "TEAD deregulation affects well-established cancer genes such as KRAS, BRAF, LKB1, NF2, and MYC, and its transcriptional output plays an important role in tumor progression, metastasis, cancer metabolism, immunity, and drug resistance." (PMID 31212916, 2019). "NF2 alteration leads to the activation of the transcription factor YAP1 and the expression of multiple downstream targets promoting tumor cell survival and proliferation." (PMID 29535838, 2018). "In mesothelioma cells with NF2-mutant and derepression of CRL4DCAF1, cell proliferation, colony formation and tumor growth in xenograft mice will all be enhanced by inactivating LATS1/2 and, hence, activating YAP in the nucleus." (PMID 27042197, 2016). "Intriguingly, we also note a significant up-regulation of several tumor suppressors in AKT1(E17K) tumors, including neurofibromin 2 (NF2), PTEN and tuberous sclerosis 2 (TSC2)." (PMID 27004402, 2016). "In summary, this study refutes the origin of vestibular tumours in NF2 as simply being on the SVN, originating as a single tumour at the transition zone along that nerve." (PMID 26104281, 2015). "Therefore, this tumor had no loss of the NF2 tumor suppressor gene." (PMID 26174772, 2015). "The interaction between T-antigen and NF2 maps to the FERM domain of NF2, which has been shown previously to be responsible for its tumor suppressor activity." (PMID 23308224, 2013). "Interestingly, mice heterozygous for a mutation at the NF2 locus (Nf2+/-) are cancer prone, and develop a wide spectrum of tumors, most frequently OS, that display strikingly high metastatic proclivity, unlike the benign tumors in human patients with NF2 syndrome." (PMID 23565227, 2013).